IL6 (interleukin 6)
Diseases named in the same sentence as IL6 in open-access papers (continued):
Sharing a sentence is not in itself a finding about the gene and the disease.
oral cancer (117 papers, 2009 to 2025). "Recent research has shown that these psychoneurological symptoms are positively correlated with inflammatory markers, such as IL-6 and C-reactive protein, in oral cancer patients, and are strongly linked to poor sleep quality and fatigue." (PMID 40282437, 2025). "SCC progression, with reference to stress in oral cancer cell lines has been linked to up-regulated IL-6 production in response to stress hormone." (PMID 38794939, 2024). "GSEA of CAFs activated by oral cancer-derived EVs revealed upregulation of several pathways linked to inflammation including TNFα, IL6_JAK_STAT3 pathway, and IL2_STAT5 signaling pathway." (PMID 37745296, 2023). "TNF- α and IL-6 was evaluated in Oral Leukoplakia against controls and was found to reveal an increased expression of TNFαin association with Oral cancer and in Oral Potentially Malignant Disorders.The concentration of TNFα had a bearing on its function." (PMID 36518124, 2022). "The present meta-analysis aimed to evaluate the association between the polymorphisms of IL-8 (-251T/A) and IL-6 (-174G/C) and the risk of oral cancer (OC)." (PMID 33922260, 2021). "In another study on patients with oral cancer, the highest levels of IL-6 in cancer tissue were found to be associated with distant metastasis." (PMID 31750257, 2019). "Lastly, salivary levels of IL-6, IL-8, IL-10, and TNFα are all increased in patients with malignant OSCC and thus are proposed to be discriminative biomarkers for oral cancer with IL-6 being associated with poor response to therapy and poor prognosis." (PMID 31572681, 2019). "Earlier studies have indicated that IL-6 is strongly associated with the development of oral cancer and there are experimental indications that anti-IL-6 receptor antibody reduces angiogenesis and tumor growth in squamous cell oral carcinoma." (PMID 31750257, 2019). "For example, the effects of MIA are mediated at least in part by IL-648 and in other systems, specifically oral cancer, IL-6 has been shown to cause global LINE-1 hypomethylation." (PMID 29967385, 2018). "We previously reported that activated IL-6 signaling was associated with the aggressive tumor behavior in oral cancer." (PMID 24625449, 2014). "Cytokine concentrations were measured by commercial enzyme linked immunoassay.Results: Salivary IL-1β and IL-6 were significantly higher in oral cancer patients than in patients with leukoplakia and control group (p<0.05)." (PMID 21743397, 2012). "Oral cancers are associated with inflammatory mediators, such as IL-6 and TNF, which potentially exert their effects through dual mechanisms, namely, by enhancing the extravasation of albumin across the capillary endothelium at the tumor site and dampening the hepatic production of albumin." (PMID 38476986, 2024). "The most common genes involved in the top 10 pathways were MAPK1, MAPK8, MAPK14, and IL6 which were seen to be associated with the MAPK signaling pathway which may be the key pathway through which andrographolide may aid in treating oral cancer." (PMID 39229580, 2024). "By cellular and xenograft tumor model using oral cancer cells, S. mutans infection was associated with the increased tumor aggressiveness, the epithelial-mesenchymal transition and interleukin-6 (IL-6) production; it also correlated with the recruitment of myeloid-derived-suppressor cells." (PMID 36186905, 2022). "In addition, some scientists assessed the relationship between IL-4 promoter and IL-6 functional genetic polymorphisms in Asian Indians and tobacco-related oral cancer." (PMID 31582940, 2019). "In this study, serum concentration of IL-6 was higher in oral cancer patients when compared to the controls which was also confirmed in other studies Furthermore, the results of this study show that serum IL-6 was an independent risk factor for the disease recurrence." (PMID 25858079, 2015).
oral cancer (continued). "Thus, the strength of the association between the IL-6 rs1800795 gene polymorphism and the oral cancer risk could be evaluated using meta-analyses, and the results of this study were more accurate than those of each independent study." (PMID 37077342, 2023). "Mechanistically, uptake of EVs derived from oral cancer cells by monocytes caused activation of the inflammatory pathway, NF-κB activation, and establishment of a pro-inflammatory and pro-tumorigenic milieu marked by increased levels of IL-6, CCL2, PEG2 and MMP9 levels." (PMID 30410681, 2018). "Science demonstrates extensive use of saliva-based testing forsystemic and local diseases such as oral cancers resulting in successful detection of IL-6, IL-8, TNF-α cytokines." (PMID 40978585, 2025). "A large group of protein biomarkers, such as interleukin-6 (IL-6), -8, -1α, and -1β, are commonly used indicators for OSCC diagnosis due to their association with lesion transformation in oral cancer." (PMID 40096320, 2025). "The first theme emphasized the importance of sensitivity and specificity, focusing on reliable biomarkers like IL-6 and miRNA for the early detection of oral cancer." (PMID 40005740, 2025). "Salivary protein biomarkers for the early diagnosis and prevention of oral cancer include IL-8, IL-6, and tumor necrosis factor α (TNF-α)." (PMID 40096320, 2025). "The presence of mucosal white lesions associated with elevated levels of inflammatory biomarkers such as IL-6, IL-8, IL-1 beta, and TNF-alpha suggests a heightened risk of oral cancer." (PMID 39097712, 2024). "Veillonella parvula is elevated in oral cancer, especially in oral squamous cell carcinoma, by promoting the expression of inflammatory cytokines, including interleukins (IL-6, IL-8) and TNF-α." (PMID 39410033, 2024). "An intriguing aspect is the suggestion that IL-6 plays a significant role in oral cancer by activating the STAT3 pathway." (PMID 38672565, 2024). "In response to areca nut exposure, IL-6 induces the production of necrotic and inflammatory cytokines, which aid in the progression of oral cancer and possibly its malignant transformation." (PMID 39027148, 2024). "MAG increased chemosensitivity to cisplatin in oral cancer cells by affecting interleukin 6 (IL-6) and STAT3." (PMID 39451517, 2024). "Elevation of inflammatory mediators, including tumor necrosis factor-alpha (TNF-α) and interleukin-6 (IL-6), has promoted cellular proliferation, inhibited apoptosis, and fostered oral cancer progression through complex signaling pathways." (PMID 38435153, 2024). "For instance, IL-6 has been demonstrated to regulate osteolytic bone invasion in human oral cancer cells." (PMID 38993553, 2024). "It has been suggested that IL-6/STAT3 signaling is essential for the survival of CSCs in oral cancer." (PMID 39272862, 2024). "Our findings highlight the crucial role of the oral microbiome in regulating key metabolic enzymes, such as CPT1A and OXSR1, as well as cytokines like TNF-α and IL-6 in oral cancer." (PMID 39456670, 2024). "One of the main etiological factors in OPMDs and oral cancer is the habit of smoking, and the decreased uric acid levels in the present study may be due to oxidative stress and the formation of oxygen radicals that cause the production of interleukin-1 (IL-1), IL-6, and TNF." (PMID 37378204, 2023). "Overall, the passage highlights the potential diagnostic value of IL-8, IL-6, and TNF-α as biomarkers for oral cancer and the upregulation of PTHLH/PTHrP in various tumors, including OSCC." (PMID 38067304, 2023). "As a consequence, several groups investigated the biomarker role of interleukins in several phases of oral cancer progression, and IL-1-β, IL-6, and IL-8 resulted in potentially predictive salivary biomarkers of OSCC progression." (PMID 36412636, 2022). "The presence of S. mutans promoted oral cancer development and progression, at least partly by increasing IL-6 production." (PMID 36186905, 2022).
oral cancer (continued). "Based on these findings, we presume that S. mutans was involved in oral cancer development and progression in an IL-6-dependent manner." (PMID 36186905, 2022). "In the clinic, proinflammatory cytokines, such as IL-6 and IL-8, exhibit a higher expression in patients with oral cancer." (PMID 34063134, 2021). "Our results showed that treatment with chrysophanol significantly decreased the expression of IL-6 and IL-8, as well as the invasion ability of oral cancer cells." (PMID 34063134, 2021). "Recently, IL-6 has been shown to stimulate migration of oral cancer cells via the phosphorylation of STAT3." (PMID 34063134, 2021). "The same group employed a similar approach for the detection of the oral cancer biomarker interleukin 6 (IL-6) protein and reported a detection limit of 0.5 pg/mL." (PMID 34940243, 2021). "Low PNI levels show poor prognosis for oral cancer because the inflammatory cytokines IL-6 and IL-8 increased the number of neutrophils and decreased those of lymphocytes besides enhancing proteolysis." (PMID 33482792, 2021). "They cultured CAFs and oral cancer cells (OCCs) isolated from a 60-year-old male patient diagnosed with oral carcinoma separately and collectively and detected the production of IL-6 and VEGF." (PMID 33003438, 2020). "The authors measured the levels of IL-1β, IL-6, IL-8 and osteopontin in whole saliva samples, which were found to be higher in patients with oral cancer than in healthy controls." (PMID 32355279, 2020). "For example, IL-6 signaling increased the protein synthesis of VEGF-C to promote lymphangiogenesis in oral cancer." (PMID 31390756, 2019). "In oral cancer, a role for an IL-6-DNMT3b axis in cell proliferation and epithelial-mesenchymal transition (EMT) and poor cancer prognosis was observed." (PMID 31771617, 2019). "In contrast, two recent studies strongly suggested a positive correlation between IL-6 and cancer development by observing much higher levels of serum IL-6 in oral cancer patients than in healthy controls." (PMID 31167516, 2019). "In vitro, IL‐6‐induced inflammation promotes tumorigenesis in oral cancer cells via aberrant DNA methylation (Gasche, Hoffmann, Boland, & Goel, 2011)." (PMID 30603107, 2018). "Several studies report higher concentrations of inflammatory cytokines in the saliva of oral cancer patients, particularly interleukin (IL)‐1β, IL‐6, and IL‐8, relative to healthy controls (reviewed by Cheng, Rees, & Wright, 2014)." (PMID 30603107, 2018). "Particularly, investigations in oral cancer cell lines have demonstrated that β2-AR signaling upregulates interleukin-6 (IL-6) mRNA, a cytokine that is involved in angiogenesis and tumor progression process, increasing proliferation and invasion of the tumor." (PMID 27042179, 2016). "Oral cancer cells can release cytokines such as interleukin-6 (IL-6) and parathyroid hormone-related peptide (PTHrP) to induce osteoclastogenesis and stimulate the production of RANKL34." (PMID 26487364, 2015). "Nevertheless, there is evidence that IL-6-induced inflammation promotes tumorigenesis in oral cancer cells by altering global LINE-1 hypomethylation." (PMID 25590298, 2015). "Co-culture of oral cancer cells with monocytic U937 cells confirmed the increased IL-6 production and the presence of S100A9 enhanced the increase." (PMID 26315114, 2015). "Together, S100A9 increased IL-6 production through the cross-talk of oral cancer cells with monocytes and the activation of NF-κB or STAT-3 participated in the release." (PMID 26315114, 2015). "By the experiments in which IL-6 signaling was suppressed by IL-6 antibody, we found that activated IL-6 signaling plays an important role in DNMT3b activation associated with activated STAT3 and PI3K in oral cancer cells." (PMID 24625449, 2014). "We therefore outlined the main signaling pathways that are thought to link IL-6 and DNMT3b to oral cancer." (PMID 24625449, 2014).
oral cancer (continued). "A recent study evaluating IL-6 levels in dogs with oral cancer revealed a baseline IL-6 value of 100 pg/ml and a mean peak level of 140 pg/ml after surgery during the observation period." (PMID 25193623, 2014). "It is reported that IL-6 levels are elevated in this neoplasm and IL-6 is considered a bad prognostic factor in oral cancer." (PMID 24625449, 2014). "The serum levels of Il-1β, Il-6 and Tnf-α are higher in patients with oral cancer than in healthy subjects." (PMID 25050571, 2014). "Salivary IL-6 was significantly higher in oral cancer patients compared to patients with leukoplakia and control group (p≤0.05)." (PMID 21743397, 2012). "Results of this study show that patients with oral cancer have higher salivary IL-1β and IL-6 concentrations compared to patients with leukoplakia and healthy controls." (PMID 21743397, 2012). "Our results show that patients with oral cancer have significantly higher concentrations of salivary IL-1β and IL-6 compared to patients with leukoplakia and healthy individuals." (PMID 21743397, 2012). "For these reasons, IL6 has become a therapeutic target and treatment with anti-IL6 antibody has resulted in complete inhibition of bone invasion of oral cancer cells in vitro and in an in vivo animal models." (PMID 23185547, 2012). "Significant differences in concentrations of salivary IL-6 and IL-8 were also observed between patients with oral cancer and patients with oral lichen planus with epithelial dysplasia." (PMID 21743397, 2012). "IL-6 is secreted constitutively by oral squamous cell carcinomas and it is found to be elevated in oral cancer patients." (PMID 20661281, 2010). "Indeed, patients with active OLP show higher salivary IL-6, and those with malignant transformation to oral carcinoma exhibit dramatically increased IL-6." (PMID 41374963, 2025). "For oral cancer, IL6 (sensitivity = 84, specificity = 72, ROC Area = 0.8816, threshold = 1.074) and CXCL1 (sensitivity = 86.67, specificity = 86.96, ROC Area = 0.8812, threshold = 0.1386) expression reached the threshold sensitivity and specificity for a strong biomarker." (PMID 38175424, 2024). "CAFs activated by oral cancer-derived EVs revealed upregulation of the pro-inflammatory gene IL-6, not seen in CAFs activated by TGFβ and iCAFs are known to secrete IL-6." (PMID 37745296, 2023). "The data indicated that there was a positive link between IL-6 expression and S. mutans infection in oral cancer cells, and induction of autophagy might contribute to the elevated IL-6 production observed in S. mutans-infected OSCC cells." (PMID 36186905, 2022). "In this study, we found that IL-6 production was induced in S. mutans -infected oral cancer cells." (PMID 36186905, 2022). "Indeed, our in vitro findings showed that chrysophanol reduced the invasion ability of oral cancer cell lines by inhibiting the expression of IL-6 and IL-8." (PMID 34063134, 2021). "Our results are consistent with previous findings where increased levels of NF-κB associated IL-6, IL-8, and TNF-α in oral cancer saliva have been reported, suggesting that OSCC progression is likely enhanced by continued expression of pro-inflammatory and pro-angiogenic cytokines." (PMID 33924500, 2021). "The pro-tumor effect exerted by S100A9 in oral cancer was in part via the increase of IL-6 expression and tumor infiltration of G-MDSCs although the involvement of other myeloid cell types and additional cytokines could not be ruled out." (PMID 26315114, 2015). "We previously reported that activated IL-6 pathways could be responsible for more aggressive tumor growth noted in oral cancer, and high activated STAT3 and p-AKT level was induced by IL-6 and linking IL-6 to tumorigenesis." (PMID 24625449, 2014). "In oral cancer cells, IL-6 was reported to promote tumorigenesis by alterinig DNA methylation." (PMID 24625449, 2014).
oral cancer (continued). "Regarding clinical data, the incidence of DNMT3b immunoreactivity in oral cancer specimens was significantly higher than in non-malignant epithelium, and positively linked to expression of IL-6." (PMID 24625449, 2014). "Activated IL-6 signaling might be responsible to the induction of DNMT3b overexpression on oral cancer." (PMID 24625449, 2014). "In conclusion, IL-6 –DNMT3b axis could be used to predict the prognosis of oral cancer in clinics, and targeting DNMT3b could represent a promising treatment strategy." (PMID 24625449, 2014). "In a recent trial of 29 consecutive patients being treated for oral cancer, it was shown that patients had much higher salivary concentration of IL-6 than controls and that this concentration increased during the treatment period returning to baseline levels at discharge." (PMID 24376459, 2013). "However, several studies reported significantly higher concentrations of serum IL-6 in oral cancer patients compared to healthy controls." (PMID 21743397, 2012). "Whether the increase of salivary IL-1β and IL-6 happens before oral cancer becomes clinically evident and whether it could be used for monitoring the malignant transformation of oral leukoplakia remains to be answered by further studies." (PMID 21743397, 2012). "IL-6 may also be responsible for tumour cell resistance to ionizing radiations in B cells or oral cancer cells, through a STAT3-dependent pathway." (PMID 19956602, 2009). "In the same way, cisplatin increased IL-6 production in erythro-leukemic or oral cancer cells." (PMID 19956602, 2009). "Thus, Basak and coworkers used an FDA-approved, turmeric-derived, curcumin-based formulation, APG-157DS, in a placebo-controlled human trial for oral cancer to demonstrate a reduction in pro-tumor cytokines IL-1β, IL-6, and IL-8 in the salivary supernatant fluid of patients with cancer." (PMID 41227348, 2025). "Moreover, the stimulation of oral cancer cells with 5-FU increases the production of IL-6 and IL-8." (PMID 37049698, 2023). "In addition, concurrent hypermethylation of multiple tumor suppressor genes by IL-6 suggests that epigenetic gene silencing may be an important consequence of chronic inflammation in oral cancer." (PMID 25590298, 2015). "Therefore, it is suggested that activation of IL-6 signaling might be responsible to the increased DNMT3b in oral cancers." (PMID 24625449, 2014). "Although we have not determined the specific nociceptive mediators released by Schwann cells following TRPV4 activation, previous studies suggest the involvement of IL-6, CX3CL1, and TNF-α from Schwann cells in oral cancer pain." (PMID 40144515, 2025). "The adipokine Chemerin can enhance the invasiveness of oral cancer cells by activating the STAT3 signaling pathway and promoting the production of IL-6 and TNF-α." (PMID 40282437, 2025). "This study observed that IL-37 exhibited potent inhibitory effects on the TNF-α-induced expression of inflammation-related genes, including IL23, IL1b, IL6, and IL17 in oral cancer cells." (PMID 40444012, 2025). "Oral cancer tissues showed significantly elevated levels of the CPT1A protein; an increased presence of T-helper cell counts (CD4+); and higher levels of OXSR1, IL-6, and TNF-α." (PMID 39456670, 2024). "In contrast, oral cancer patients demonstrated elevated concentrations of key markers, including CPT1A, IL-6, OXSR1, and TNF-α, reflecting substantial alterations in metabolic and inflammatory pathways." (PMID 39456670, 2024).